KMT2B (lysine methyltransferase 2B)
Diseases named in the same sentence as KMT2B in open-access papers (continued):
Sharing a sentence is not in itself a finding about the gene and the disease.
cancer (36 papers, 2014 to 2025). A tumor composed of atypical neoplastic, often pleomorphic cells that invade other tissues. "HBV integrations have also been found to alter other cancer‐associated genes, including lysine methyltransferase 2B (KMT2B) and Cyclin E1 (CCNE1)." (PMID 39720865, 2025). "Mutations in epigenetic modifier enzymes KMT2B, KMT2C, KMT2D, and ARID1A were more prevalent in MSI cancers, where the majority possessed KMT2B and KMT2D mutations and over one-third had KMT2C and ARID1A mutations (χ2 test p = 0.001)." (PMID 37998722, 2023). "A subsequent bioinformatics analysis revealed cancer-associated somatic mutations, including KMT2B c.7804A > G DNA (protein: p.Ile2602Val) and MGA c.3628C > G DNA (protein: p.Arg1210Gly) with allele frequencies of 13.06% and 6.12%, respectively." (PMID 31882696, 2019). "Mutation of KMT2B in cancers frequently leads to upregulated levels." (PMID 38347590, 2024). "Additionally, the expression levels of cancer-associated genes, such as hTERT, KMT2B, MLL4, CCNE1 and PAK3, were found to be up-regulated in tumor tissues compared to their corresponding normal counterparts." (PMID 39148134, 2024). "Moreover, KMT2B carries similar mutations in cancers, which are predominantly missense, nonsense, and frameshift affecting the SET and PHD domains." (PMID 33302406, 2020). "Analysis of the TCGA and GTEx datasets containing 179 PDACs and 171 non‐tumour pancreatic tissues revealed there was an obvious elevation in the mRNA level of KMT2B in cancer tissues (p < .05)." (PMID 40741875, 2025). "Although increased expression levels of KMT2B have been reported in various cancer types, including HCC, colorectal cancer and gastric cancer, its role in cancer development remains investigation." (PMID 40741875, 2025). "KMT2B is an important methyltransferase gene that contributes to chromatin remodeling dysfunction in various cancers." (PMID 37920164, 2023). "We presented a comprehensive characterization of KMT2A, KMT2B, KMT2C, and KMT2D pathogenic variation in a large cancer‐free adult population, with ancestry‐ and sex‐specific frequencies." (PMID 36479909, 2023). "According to the database, among the KMT2A-D proteins, KMT2C is the most frequently mutated (~ 4 050 cases of cancer patients), followed by KMT2D (~ 2 600 cases), KMT2A (~ 1 580 cases), and finally KMT2B (~ 1 250 cases)." (PMID 36598580, 2023). "The current study supports the role of KMT2B in cancer metastasis and indicates that KMT2B facilitates the bone metastasis of CC." (PMID 36594087, 2023). "Genotype–phenotype correlations have been established between KMT2A (11q23.3), KMT2B (19q13.12), KMT2C (7q36.1), and KMT2D (12q13.12) somatic variants and different cancer types." (PMID 36479909, 2023). "Other cancer-related genes with recurrent insertions within gene boundaries are KMT2B (n = 4, three in coding exons) and CCNE1 (n = 2, all intronic), both at chromosome 19q." (PMID 34824211, 2021). "Other genes like CCNE1, SENP5, FN1, KMT2B, and DUX4 were alsoidentified by HGT-ID; these genes were previously reported to be associated with tumorigenesis or cancer invasion." (PMID 30016933, 2018). "Ki‐67 staining indicated that KMT2B promoted cancer cell proliferation (p < .05)." (PMID 40741875, 2025). "Similarly, an analysis of the genomic landscape of MSI-H in 11,395 tumors across 30 cancer types showed that mutations in ACVR2A (73%), KMT2D (68%), KMT2B (66%), and MMR-related genes were enriched in the MSI-H group." (PMID 38281914, 2024). "There are a few studies showing the role of KMT2B in cancer metastasis." (PMID 36594087, 2023). "Furthermore, in 18 types of cancer, KMT2B and KMT2F were mostly upregulated, whereas the other KMT2s were primarily downregulated." (PMID 35058979, 2022). "Notably, genomic clusters of viral integrations were identified in TERT (number of integration sites within a genomic cluster (NGC) of 6), KMT2B (NGC = 4)—which was recently identified to be a likely cancer driver gene—and RGS12 (NGC = 3)." (PMID 32025001, 2020).
cancer (continued). "In the unclassified subgroup, apart from previously reported mutations in epigenetic regulators in multiple cancers, including KMT2C, KMT2D, KMT2B, PRDM2, NCOR2, KAT6B, and EP300, in this cohort, we also found new recurrent mutations in epigenetic regulators, including CREBBP and PRDM16." (PMID 30950204, 2019). "Sequencing results showed that MET, EGFR, KMT2B and RET gene were mutated in LGFM, and KMT2B gene had cancer promoting effect, but there was no literature report in LGFM, which may be of certain significance for the diagnosis and treatment of LGFM." (PMID 38347522, 2024). "In contrast to KMT2A and KMT2B, KMT2C and KMT2D inhibit cell proliferation and are often considered tumor suppressors in different types of cancer." (PMID 38791111, 2024). "In a pan-cancer study evaluating the -intra and -inter tumor heterogeneity of the KMT2 gene, it was noted that KMT2B expression was significantly upregulated in 18 tumor types, including BC subtypes, which correlated with an aggressive phenotype." (PMID 38347590, 2024). "Integration events occurring in single samples were observed in the following cancer-driver genes: TERT, KMT2B (MLL4), RIMS1, FN1, RBFOX1, CNTNAP2 and THRB7,11,12,14,27,28." (PMID 37400627, 2023). "The most prevalent altered cancer-related genes were CTNNB1 (16%) and ZNRF3 (16%), followed by EGFR (11%), JARID2 (11%), KMT2B (11%), KMT2C (11%), NSD1 (11%), PIK3CA (11%), SH2B3 (11%), and UBR5 (11%)." (PMID 38023213, 2023). "Integrations occurred in the known cancer driver genes CCNA2, (four cases), TERT (one case), CCNE1 (three cases), TNFSF10 (two cases) and KMT2B (one case), leading to overexpression of the target genes." (PMID 36316711, 2022). "Although not previously reported in osteosarcomas, mutations in KMT2B/MLL2, KMT2C/MLL3, or KMT2D/MLL4 that catalyze mono‐ or di‐methylation of H3K4 are frequently observed in many types of cancer." (PMID 35920001, 2022).
tumor (27 papers, 2016 to 2025). "Moreover, patients showing modifications of CEBPA, FGFR4, MET or KMT2B genes detected in circulating tumor DNA before ICI initiation are at higher risk of experiencing irAEs." (PMID 36900420, 2023). "Our research discovered that all members of the KMT2 family were linked with subtypes of immune invasion in the tumor microenvironment, with KMT2B and KMT2F being associated with more aggressive subtypes of immune invasion, notably C1, C2, and C6, and poor prognosis." (PMID 35058979, 2022). "KMT2B is known to be associated with infantile leukemia and tumor cell proliferation." (PMID 35058979, 2022). "The in vivo role of KMT2B in tumour growth and metastasis was evaluated in subcutaneous and orthotopic mouse models of human PDAC." (PMID 40741875, 2025). "In conclusion, our study identifies mutations in LRP1B, KMT2B, TSC2 and BRAF as significant prognostic markers in T1/2 CRC, along with critical clinical features such as lymphovascular invasion, poor tumour differentiation and aggressive histological types." (PMID 39777996, 2025). "At the sacrifice time, overexpression of KMT2B resulted in a more than threefold increase in tumour weight compared to the control group (.11 ± .07 g vs. .34 ± .20 g, p < .05)." (PMID 40741875, 2025). "To understand the potential mechanisms underlying the tumour‐promoting function of KMT2B, we first compared the mRNA expression profiles between the PANC‐1‐KMT2B and the PANC‐1‐VC control cells." (PMID 40741875, 2025). "IHC analysis of a tissue microarray, comprising 80 PDACs and 70 adjacent non‐tumour tissues, confirmed a significant elevation of KMT2B protein levels in PDACs (p < .01)." (PMID 40741875, 2025). "Gene ontology (GO) analyses of the RNA-seq data revealed that the upregulated pathways in KMT2B and KMT2D KD BCCs were associated with tumor progression, e.g., inflammatory cues and cell migration." (PMID 38347590, 2024). "Collectively, the results showed that KMT2B and KMT2D KD changed the transcriptional landscape of BCCs; particularly, upregulating genes associated with tumor growth." (PMID 38347590, 2024). "In contrast, the knockdown of KMT2B significantly decreased the growth rate after 15 days of tumor growth, resulting in a 43% reduction in tumor weight (0.22 ± 0.085 g vs. 0.39 ± 0.089 g, p < 0.05) at the time of sacrifice (21 days post-inoculation)." (PMID 36594087, 2023). "In the subcutaneous model of human CC, KMT2B overexpression significantly promoted tumor growth and increased tumor vascular density." (PMID 36594087, 2023). "Compared with paired non‐tumor tissues, KMT2B was found to be significantly upregulated in GC tissues (P < 0.05)." (PMID 35592651, 2022). "HBV integration sites in the KMT2B gene are more frequent in tumor samples, while it has been reported that the gene is upregulated in tumor samples relative to the adjacent normal tissue samples." (PMID 34442866, 2021). "Cluster 9 also included all microsatellite instable (MSI) ENOC tumours, and was also associated with MMRD-1, Age, and Del signatures, along with higher numbers of SNVs, and KMT2B and RPL22 mutations." (PMID 30794536, 2019). "For example, KMT2B expression level was higher in tumor tissues in which HBV-KMT2B fusion transcripts were detected." (PMID 29212479, 2017). "The pro‐tumour effects of the KMT2B/FYN axis are mediated by the PI3K/Akt signalling pathway." (PMID 40741875, 2025).
tumor (continued). "Similarly, a significantly increased mRNA level of KMT2B was shown in 22 human PDAC samples compared to the 18 non‐tumour tissue samples (p < .05)." (PMID 40741875, 2025). "In our study, KMT2B significantly increased tumor progression in the late stage (after 14 days) compared to the control group, suggesting that KMT2B might promote tumor growth in vascular stage." (PMID 36594087, 2023). "Moreover, integration into the TERT, CCNA2, CCNE1, and KMT2B genes is more common in the HCC group than in the non-tumor group infected with HBV." (PMID 36992198, 2023). "Together, based on our present researches, KMT2B-targeted therapy may be beneficial to CC patients with high KMT2B expression by inhibiting local tumor growth via impairing angiogenesis." (PMID 36594087, 2023). "The insertion of HBV DNA into the CCNA2 and CCNE1 genes, which are associated with the G1/S transition of the cell cycle, disrupts the biological process and promotes tumor development; KMT2B is a tumor suppressor gene that prevents the uncontrolled growth and division of cells." (PMID 36992198, 2023). "Among these alterations, we identified KMT2B S421P and NOTCH1 T2483 missense mutations, which may have an important role in pathogenesis of this tumor model given the previously established role of these genes in tumorigenesis." (PMID 34051734, 2021). "Another tumor-promoting component of COMPASS-like complex genes affecting the SET and PHD domains is KMT2B, which is less studied." (PMID 38791111, 2024). "For example, some known oncogenes, such as KMT2B and TERT, were dominantly observed in tumor while fusion transcripts with CYP3A5, SERPING1, and WDR72 were only found in normal tissue." (PMID 29212479, 2017). "Among the 24 patients with integration in the tumor, we found that a significant proportion of the integrations, especially those in the hotspot regions around TERT and KMT2B (MLL4), were often truncal events that happened in the early history of tumorigenesis." (PMID 35382356, 2022). "In contrast, the expression of KMT2B and KMT2G in C6 components was higher than that in C5, suggesting that these genes may act as tumor promoters." (PMID 35058979, 2022). "Transcription factors like NOTCH1 (16%) and KMT2B (16%), UNC13C (14%), another tumor suppressor, ERCC2 (14%) involved in nucleotide excision repair pathway, were recurrently mutated, whereas genes like CDKN2A, MLH1, FGFR1, EGFR, etc. had a less than 10% mutation frequency." (PMID 34796107, 2021). "Similarly, KMT2B and TSC2 mutations, although not well‐studied in CRC, have been implicated in other malignancies for their roles in enhancing tumour aggression and stemness, further supporting their inclusion as high‐risk markers in our model." (PMID 39777996, 2025). "Some non-canonical tumor suppressors, like lysine methyltransferase 2B (MLL4), have also been shown to play a role in ferroptosis-mediated tumor suppression, as well." (PMID 41514908, 2025).
movement disorder (4 papers, 2017 to 2025). Neurological conditions resulting in abnormal voluntary or involuntary movement, which may impact the speed, fluency, quality and ease of movement. "With some exceptions (e.g., ADCY5-, KMT2B-, ATP1A3-related movement disorders), the number of reported patients affected by these novel genetic entities is still rather limited." (PMID 29086067, 2017).
neurodevelopmental disorder (3 papers, 2021 to 2024). A behavioral and cognitive disorder with onset during the developmental period that involves impaired or aberrant development of intellectual, motor, or social functions. "KMT2B-related disorders share many overlapping phenotypic characteristics with other neurodevelopmental disorders and delayed dystonia, that can appear later in childhood, often delaying clinical diagnosis." (PMID 38425714, 2024).
genetic disorder (2 papers, 2022 to 2025). "In this study, we describe the clinical and genetic features of the largest cohort of patients reported to date with KMT2B mutations, thereby elucidating a number of new and important concepts for this recently identified genetic disorder." (PMID 39990802, 2025). "Apart from KMT2A, three other CXXC-domain-containing epigenetic regulators have been linked to Mendelian diseases: KMT2B (DYS28; OMIM:617284), DNMT1 (HSN1E; OMIM:614116), and TET3 (BEFAHRS; OMIM:618798)." (PMID 35727845, 2022).
KMT2B also shares sentences with these, for which no sentence is quoted: neurological disorder (3 papers); developmental delay (2); autism spectrum disorder (1); autosomal dominant cerebellar ataxia (1); B-cell lymphoma (1); Beck-Fahrner syndrome (1); childhood-onset Dystonia-28 (1); Cirrhosis (1); cognitive deficits (1); deafness (1); endometrial cancer (1); episodic ataxia (1); giant cell tumor (1); Hepatic cysts (1); hereditary sensory neuropathy type IE (1); laryngeal dystonia (1); Lesch Nyhan disease (1); lung adenocarcinoma (1); lung carcinoma (1); melanoma (1); narcolepsy (1); Neurodevelopmental delay (1); neurogenetic disease (1); O'Donnell-Luria-Rodan syndrome (1); oromandibular dystonia (1); pantothenate kinase-associated neurodegeneration (1); Wiedemann-Steiner syndrome (1).